DLL4 (delta like canonical Notch ligand 4)
Diseases named in the same sentence as DLL4 in open-access papers (continued):
Sharing a sentence is not in itself a finding about the gene and the disease.
tumor (continued). "The DLL4 overexpression showed fewer but larger vessels whereas JAG1 upregulation produced more vessels in tumor cells." (PMID 32046779, 2020). "In one case, exosomal Dll4 retained its activity as a functional Notch ligand, being still able to activate Notch receptors in signal-receiving tumor cells." (PMID 33198378, 2020). "Compared to the vehicle group, DLL4-positive tumor vessels were reduced by 40% in the irinotecan group, by 72.5% in the mABL001 group, and by 87.5% in the combination group." (PMID 33383646, 2020). "DLL4, as a main Notch ligand, is overexpressed in tumor vascular epithelial cells and tumor cells to activate the Notch pathway in many solid tumors." (PMID 32742191, 2020). "In 2006, two reports were published in Nature revealing the paradoxical phenotype of inhibiting Dll4 in restricting tumor growth." (PMID 33198378, 2020). "By contrast with the VEGF blockade, Delta-like ligand 4 (Dll4) inhibitors resulted in increased tumor vessel density, characterized by sprouting and proliferating small vessel branches." (PMID 33198378, 2020). "MiR-182-5p plays tumor-suppression and anti-angiogenesis roles through altering the microenvironment and regulating DLL4 expression." (PMID 31996265, 2020). "Notch signalling is a major regulator of sprouting angiogenesis and the balance between DLL-4 and Jagged-1 has an impact on the tumour vascular architecture." (PMID 32575680, 2020). "The DLL4/Notch signaling pathway can be a promising target of the next angiogenesis inhibitors, as this pathway regulates tumor angiogenesis with a different mechanism of action compared to that of the VEGF inhibitors." (PMID 33383646, 2020). "In colon cancer transplant mouse models, Dll4 and Jagged1 presence in tumor endothelial cells was found to activate Notch1 in neighboring tumor cells." (PMID 33198378, 2020). "Molecularly targeting DLL4 expression on tumor vasculature with antibody conjugated TNPs recovered PTT sensitivity in otherwise therapy resistant SSIL2Rγ- (DLL4-high) strain." (PMID 32373218, 2020). "Analysis of tumor growth inhibition (TGI) by bioluminescent imaging revealed strong TGI in SSIL2Rγ- rats treated by anti-DLL4-conjugated TNPs followed by PTT." (PMID 32373218, 2020). "DLL4-positive tumor vessels were significantly reduced in the combination group compared to other groups." (PMID 33383646, 2020). "This strategy can be an effective treatment in most of the tumor models that overexpress endothelial DLL4." (PMID 32373218, 2020). "In contrast, expression of DLL1 or DLL4 in DC was positively correlated with the expression of Notch receptors on tumor-infiltrating Tem cells." (PMID 30940183, 2019). "Intriguingly, forced expression of DLL4 in tumor cells affects the morphogenesis of tumor vasculature, leading to the non-functional angiogenesis in the TME." (PMID 31739580, 2019). "In lung cancer, VEGF directly affects expression of Dll4 in tumor vessels, as well as in neuroblastoma models, where blocking VEGFR2 increases the level of Jagged1 expression and consequent Notch1 hyperactivation." (PMID 30917608, 2019). "Accordingly, we showed that OMP-52M51 reverts the strong induction of gene signatures related to tumor cell migration and adhesion upon Notch1 activation and prevents DLL4-stimulated migratory capacity of MCL cells." (PMID 31676012, 2019). "As2O3 disturbed the morphological development of tumor vessels and downregulated the protein levels of delta-like canonical Notch ligand 4 (Dll4), Notch1, and Hes1 in vivo." (PMID 31093499, 2019). "We determined the protein level of the Notch pathway-related factors in tumor tissues and found that As2O3 reduced the protein levels of Dll4, Notch1, and Hes1 in vivo." (PMID 31093499, 2019). "DLL4 acting through Notch1/4 plays key roles such as regulating endothelial cells during normal and tumour angiogenesis." (PMID 31589383, 2019).
tumor (continued). "Several studies demonstrate that one such regulator essential for tumor neovascularization is the NOTCH ligand DLL4, which is one of three delta-like ligands in the mammalian genome." (PMID 30691003, 2019). "VEGF and Dll4, a Notch ligand, emerge as the yin and yang of angiogenesis for embryonic vascular development and tumor angiogenesis." (PMID 32038259, 2019). "Monoclonal antibodies against DLL4 used to target the tumor vasculature, result in an increase of branched vessels but with decreased functionality." (PMID 30087852, 2018). "Notch signaling has an undisputable participation in tumor vessel creation and particularly Jagged-1 and Dll-4 are crucial ligands for this procedure affecting both cancer cells and neighboring components." (PMID 30111989, 2018). "Blockade of DLL4 in glioma and breast tumors delays tumor growth even in those tumors that are resistant to anti-VEGF therapy." (PMID 30087852, 2018). "Tumor-infiltrating myeloid cells activate Dll4/Notch/TGF-β signaling to drive malignant progression." (PMID 29915603, 2018). "In multivariate analysis, high VM, Notch4, DLL4 levels, tumor size, LNM, DM, TNM stage, and low KAI1/CD82 levels were potential to be independent prognostic factors for overall survival time (OST) in NSCLC patients." (PMID 30593175, 2018). "In a phase I clinical trial, enoticumab, a Dll4 monoclonal antibody targeting the tumor vasculature, showed stable disease as best response in 2 of the 6 breast cancer patients enrolled." (PMID 30515368, 2018). "Tumor-derived VEGF induces Dll4 expression in tumor vessels resulting in increased number of stalk cells, characterized by high Notch activity, at the expense of the tip cells." (PMID 30154786, 2018). "In the TNBC UM-PE13 xenograft, blockage of DLL-4, decreasing Notch1 signaling, resulted in delayed tumor regrowth after paclitaxel treatment, with additionally decreasing the CSC frequency." (PMID 30515368, 2018). "DLL4 has been shown to be both important for tumor vasculature as well as for maintaining tumor-initiating capacity of tumor stem cells in various tumor models." (PMID 30087852, 2018). "Evaluation of primary tumor drug accumulation revealed that doxorubicin accumulation was increased by 60% when endothelial cells were overexpressing Dll4." (PMID 28288569, 2017). "Given the critical role of Dll4 on tumor angiogenesis, we analysed the tumor vasculature, hypoxia and apoptosis in the endothelial and ubiquitous mutants." (PMID 28086833, 2017). "Bevacizumab profoundly pruned the vessels leaving behind surviving vessels that expressed high levels of DLL4 in all three types of tumours (VII-IX)." (PMID 28445154, 2017). "Several evidence reported that in vivo hypoxia upregulated expression of Dll4, Jagged1, Notch1, Notch4, Hes1, and Hey which in turn promoted tumor angiogenesis." (PMID 28157712, 2017). "When comparing lean and obese in the type I tumor only, significantly higher expression in Notch1, Notch4, DLL4, OB-R, and IL-1R tI were found in obese patients (p < 0.05)." (PMID 28659656, 2017). "In vivo, both mDLL4 and mJAG1 increased the expression of DLL4 in tumour tissues but there was more induction by mDLL4 than by mJAG1." (PMID 28445154, 2017). "We have previously shown that knock‐down of CCM3 stimulated endothelial angiogenesis via impairing DLL4‐Notch signalling; moreover, loss of endothelial CCM3 stimulated tumour angiogenesis and promoted tumour growth." (PMID 28371279, 2017). "Our evidence suggests that Dll4/Notch signaling amplification stabilizes tumor vessels by enhancing EphrinB2/EphB4 and PDGF/ PDGFRβ signaling and, therefore, promoting vascular maturation." (PMID 28288569, 2017). "Many studies have focused on the effects of endothelial DLL4 or JAG1 on tumour growth and vascularisation." (PMID 28445154, 2017). "Evaluation of doxorubicin concentration in the primary tumor revealed that endothelial Dll4 overexpression improved drug accumulation by 60% (p < 0.01)." (PMID 28288569, 2017).
tumor (continued). "Blocking DLL4-Notch signalling with anti-DLL4 mAb significantly delayed tumour growth and increased mouse survival in both EV- and mJAG1-tumours." (PMID 28445154, 2017). "The mechanism behind the differential responsiveness was due to a positive feedback loop for DLL4-Notch signalling, rendering DLL4 more dominant in activating Notch signalling in the tumour microenvironment." (PMID 28445154, 2017). "Inhibition of Dll4 and Notch signaling leads to functionally compromised vessels and suppresses tumour growth." (PMID 28193190, 2017). "We observed ectopic expression of Dll4, Notch2 and 4 and Hes5 in the small intestine tumor epithelium." (PMID 28086833, 2017). "To further investigate the interplay between JAG1 and DLL4 in promoting tumour growth, we used specific anti-DLL4 mAb (MedImm) that recognises both human DLL4 and mouse DLL4 to block DLL4-induced Notch signalling in mJAG1-expressing tumours." (PMID 28445154, 2017). "Ubiquitous and endothelial-specific Dll4 deletion led to an equivalent reduction of tumor growth because of a similarly marked tumoral angiogenic phenotype promoting non-productive vasculature and consequently hypoxia and apoptosis." (PMID 28086833, 2017). "In fact, we found previously that EphB4-EphrinB2 signalling activated in DLL4-expressing tumours is, to some extent, responsible for the increased vessel size and tumour resistance to anti-VEGF therapy." (PMID 28445154, 2017). "DLL4 is predominantly expressed in the ECs of tumour blood vessels but also in a small proportion of tumour cells; whereas JAG1, although also expressed in ECs, is more highly expressed in tumour cells and mural cells." (PMID 28445154, 2017). "To investigate this further, we treated the mJAG1-tumours with anti-DLL4 blocking antibody that recognises both human DLL4 and mouse DLL4." (PMID 28445154, 2017). "Dll4 expression was most pronounced in the tumor cells but it was also present in the tumor blood vessels and in other stromal cells." (PMID 28086833, 2017). "Tumor growth was reduced by both endothelial Dll4 overexpression and doxorubicin administration to Dll4BE mice, while the concomitant administration of doxorubicin to Dll4OE mice further reduced the tumor growth by 15% at endpoint (p < 0.05)." (PMID 28288569, 2017). "Both JAG1 and DLL4 are up regulated in several cancer cells and can control neovascularization and stimulate tumor growth in mice." (PMID 28533486, 2017). "DLL4 has been shown to inhibit sprouting resulting in fewer but better perfused blood vessels, which promoted tumour growth." (PMID 28445154, 2017). "DLL4 stained positively on tumour and/or stromal cells, and increased especially in cells surrounding tumour vessels when EV-tumours and mJAG1-tumours were treated with bevacizumab (VII and IX) as well as treated with the combination (X and XII)." (PMID 28445154, 2017). "Regarding DLL4, its high expression in tumor cell lines has been reported to reduce vascular density." (PMID 28533486, 2017). "Increased DLL4 expression was observed in EV-tumours treated with bevacizumab compared to control (VII versus I) as DLL4 is induced by hypoxia through HIF-1α." (PMID 28445154, 2017). "DLL4 expression was also very high in mDLL4-tumours, confirming the over-expression in these cells, but also in the vessels (II, V, VIII and XI), suggesting a positive feedback loop." (PMID 28445154, 2017). "Given the potential promise of DLL4 inhibition for anti-tumor activity, a second approach was then undertaken by engineering a Fab’2 fragment to target DLL4 (rather than inhibition of DLL4 with the full IgG1 antibody)." (PMID 28475417, 2017). "WB analyses of pooled tumor lysates showed that PC xenografts derived from leptin treated-tumorspheres had significantly higher levels of Notch4, DLL4, JAG1, survivin, PCNA and Oct-4." (PMID 27999190, 2017).
tumor (continued). "We found that increased Dll4/Notch signaling reduces tumor growth by reducing vascular endothelial growth factor (VEGF)-induced endothelial proliferation, tumor vessel density and overall tumor blood supply." (PMID 28288569, 2017). "We observed a different expression pattern of Dll4, all Notch receptors (with regional variation) and Hes5 in the tumor epithelium." (PMID 28086833, 2017). "Transduced malignant cells that over-express membrane Dll4 (entire molecule or functional extra-cellular portion) were previously found in subcutaneous tumor grafts to result in reduced tumor vessel density and produce wide, straight and less branched vessels." (PMID 28288569, 2017). "In xenograft models of CRC anti-Dll4 therapy seems to additionally reduce the frequency of tumor stem cells." (PMID 28086833, 2017). "Results revealed that endothelial Dll4 overexpression and the independent administration of doxorubicin, a common chemotherapeutic drug, were equally effective in reducing tumor burden and the formation of distant-site metastasis." (PMID 28288569, 2017). "Dll4 was strongly expressed on the front of growing vessels in vascularised tumors and Dll4 expression in tumor vessels was rapidly decreased after blocking VEGF." (PMID 28284219, 2017). "Previous work showed that the inhibition of Dll4/Notch represses tumor growth by promoting dysfunctional an immature tumoral angiogenesis in a variety of xenograft and autochthonous mouse models." (PMID 28086833, 2017). "Dll1 and Dll3 seemed less expressed in the tumor epithelium, and Dll4, all Notch receptors, and Hes1 seemed upregulated." (PMID 28086833, 2017). "We found that in the ApcMin/+ small and large intestine, Dll4 is strongly expressed in the tumor epithelium, including in the goblet and Paneth cell lineages, and it is also present in the tumor endothelium." (PMID 28086833, 2017). "This indicates that besides the effect on angiogenesis, Dll4/Notch signaling seems to have an additional role maintaining the tumor stem cells undifferentiated." (PMID 28086833, 2017). "CSPCs can advance to a heterogeneous lineage of cancer cells, ultimately forming tumors 24; therefore, we suggest that elevated DLL4 levels promote gastric CSPCs and tumor formation." (PMID 27891816, 2017). "In support of this, a recent study has shown that the combination of DLL4‐Notch and EphrinB2/EphB4 targeted therapy is highly effective in disrupting tumour angiogenesis." (PMID 28371279, 2017). "Endothelial-specific and ubiquitous Dll4 deletion were more effective reducing tumor number than individual tumor growth, both in the small and large intestine." (PMID 28086833, 2017). "Data from a Phase1 clinical trial showed that Demsizumab (anti-Dll4) suppressed tumor vascularization, was well tolerated and resulted in reduced tumor size." (PMID 26713603, 2016). "In fact, blockade of DLL4-Notch signaling is an emerging therapeutic approach to inhibiting tumor angiogenesis." (PMID 26823670, 2016). "In cancer, Dll-4-Notch signaling pathway regulates tumor growth by decreasing angiogenesis, despite improving vascular function." (PMID 27608016, 2016). "In a previous study, we developed a murine anti-human DLL4 monoclonal antibody with expected anti-angiogenesis and anti-tumor effects." (PMID 27301650, 2016). "This decoy also has anti-tumour effects most likely due to mechanisms already discussed with Dll4 blockade." (PMID 26620208, 2016). "As shown in this study, the down-regulation of DLL4 is also drastic in tumor samples derived from breast, brain, kidney, lung, liver, and prostate." (PMID 27542210, 2016). "In conclusion, H3L2 is an ideal humanized antibody that inhibits tumor growth through targeting DLL4-Notch pathway and has attracting potentials for clinical applications." (PMID 27301650, 2016).
tumor (continued). "Among the ligands, inhibition of Dll4 has shown the most promising results, based on its effect on tumor angiogenesis and, in some case, on tumor cells directly (e.g. inhibition of cancer stem cells)." (PMID 26934331, 2016). "Although blocking Dll4 has shown anti-tumour responses in these pre-clinical models, the aberrant effects of chronic Dll4 inhibition have also been investigated." (PMID 26620208, 2016). "Alteration of the expression of Notch ligands Jagged1, which enhances tumor angiogenesis, and DLL4, which acts as negative regulator of tumor vasculogenesis, has been discovered in various tumors." (PMID 26788072, 2016). "The aim of this study is to humanize a murine antibody MMGZ01 targeting DLL4 and evaluate its anti-tumor activity." (PMID 27301650, 2016). "Notch signaling components are expressed in tumor endothelial cells, but the most notable component in this class is DLL4." (PMID 26823670, 2016). "Further experiments confirmed that increasing the amount of Vegfa also reduces blood vessel branching in tumours in mice by synchronizing the fluctuations in the levels of Dll4 in neighbouring endothelial cells." (PMID 27074663, 2016). "The Notch ligands JAG1 and Dll4 and the Notch receptors Notch1–4 are functionally overexpressed in KS tumor cells." (PMID 27760204, 2016). "These antibodies are able to target cancers by inhibiting simultaneously cancer cell growth and by disrupting tumor angiogenesis that depends on DLL4/Notch1 signaling." (PMID 26713603, 2016). "Nevertheless humanised anti-Dll4 antibodies (demcizumab) are currently undergoing clinical trial evaluation in various tumour types." (PMID 26620208, 2016). "The Notch ligands JAG1 and Dll4, and the Notch receptors Notch1–4 are highly expressed in KS tumor cells." (PMID 27760204, 2016). "Our result showed that tumor lesions in HBV-infected HCC have increased level of Notch1 (50%), Dll4 (62.5%), and Jagged1 (12.5%), compared to non-tumor lesions." (PMID 26766040, 2016). "An experimental proof for this comes from pre-clinical studies using Dll4-targeting antibodies, a therapeutic approach pursued by different biotech companies due to its powerful effect on tumor growth primarily via angiogenesis dysregulation." (PMID 26934331, 2016). "Along this line, Dll4 blocking antibodies have been used to suppress tumor vascularization and tumor growth." (PMID 26713603, 2016). "Potentiated Notch signaling due to either loss of a negative regulator or increased expression of the Notch activating ligand Dll4 in the tumor vasculature correlates with tumorigenesis and therapeutic resistance." (PMID 26755662, 2016). "The results indicates that H3L2 inhibited tumor growth through blockage of DLL4-Notch signaling pathway." (PMID 27301650, 2016). "The plot also shows the final value of the relative growth gre, showing that the tumor grows more slowly when Dll4 is blocked, even if the vascular network is denser." (PMID 26891163, 2016). "DLL-4 inhibition promotes the formation of new blood vessels that establishes the role of DLL-4 against tumor angiogenesis." (PMID 26762567, 2016). "Intriguingly, overexpression of Dll4 in tumour cells has been shown to lead to reduced vessel branching and dramatically increased tumour vessel diameter, with evidence that tumour cell Dll4 activates endothelial Notch receptors." (PMID 27074663, 2016). "This Dll4 inhibition was anti-angiogenic and showed anti-tumour effects in six different tumour models." (PMID 26620208, 2016). "Dll4 has been found to be upregulated in the vessels of tumour xenografts and also in the vessels of human tumours suggesting a good target for anti-angiogenic agents." (PMID 26620208, 2016). "Recent studies also report that Notch activation is evident during the overexpression of DLL4 resulting in the reduction of tumor growth and vascularization." (PMID 27542210, 2016).